RN7SL28P (RNA, 7SL, cytoplasmic 28, pseudogene)
Gene: Miscellaneous RNA gene on chromosome 4 (184,278,936 to 184,279,233, forward strand). Ensembl gene ENSG00000244512.
Homologues: Orthologues: chimpanzee Metazoa_SRP (99% identical), macaque Metazoa_SRP (96% identical). Paralogues in human: RN7SL1 (83% identical), RN7SL2 (83% identical), RN7SL126P (82% identical), RN7SL3 (82% identical), RN7SL220P (81% identical), RN7SL498P (81% identical), RN7SL357P (80% identical), RN7SL679P (80% identical), RN7SL397P (80% identical), RN7SL559P (80% identical), RN7SL464P (80% identical), RN7SL709P (80% identical), and 700 more.